IL5 (interleukin 5)
Diseases named in the same sentence as IL5 in open-access papers (continued):
Sharing a sentence is not in itself a finding about the gene and the disease.
fibromyalgia (3 papers, 2021 to 2024). A chronic disorder of unknown etiology characterized by pain, stiffness, and tenderness in the muscles of neck, shoulders, back, hips, arms, and legs. "Of interest, IL-5 has been associated with pain in fibromyalgia." (PMID 38585275, 2024). "In an experimental model of fibromyalgia, IL-5 elicits an analgesic effect through inducing macrophage polarization toward M2 anti-inflammatory phenotype (CD206+) serving as a potential strategy to alleviate the pain along with other fibromyalgia-associated somatic symptoms." (PMID 37069462, 2023). "For instance, T helper 2 (Th2) anti-inflammatory cytokines, including IL-4, IL-5 and IL-13, have been reported to decrease in fibromyalgia patients, whereas inflammatory cytokines IL-6 and IL-8 are found to elevate in fibromyalgia, indicating a potential role in the chronic pain of fibromyalgia." (PMID 33912165, 2021). "While no increase in IL-5 was observed in a mouse model of fibromyalgia (acidic saline injected in the gastrocnemius), i.v. injection of IL-5 improved the mechanical thresholds of the paw, sign of a decrease in pain." (PMID 38585275, 2024).
gastritis (3 papers, 2024). Inflammation of the stomach. "Furthermore, it has been observed that ILC2s produce IL-5 to mediate the IgA response in the early stages of HP infection, thereby eliminating pathogenic HP and thus inhibiting the development of gastritis." (PMID 39309440, 2024). "Although the levels of IL-5, IL-6, IL-9, IL-10, IL-13, and IL-21 were higher in patients with gastritis than Hp- group, this increase was not significant." (PMID 39807418, 2024).
gingivitis (3 papers, 2014 to 2021). A disorder involving inflammation of the gums; may affect surrounding and supporting structures of the teeth. "In subjects with gingivitis, compared with the Cg group, levels of inflammatory factors IFN-γ, IL-4, IL-5, IL-6, IL-10 and IL-13 were significantly lower in saliva in the Dg group (p<0.05)." (PMID 33417619, 2021).
hematoma (3 papers, 2014 to 2023). A hematoma is a collection of blood from a vascular structure into an extravascular space. "When using the IL-5 cutoff as a predictor in a univariate logistic regression model of hematoma thickness >20 mm, it accounted for 85% of the variance (R2 = 0.85, p < 0.001)." (PMID 36974123, 2023). "In the earlier prospective cohort study of these two researchers on 57 patients, an association between increased hematoma fluid (but not serum) of a panel of biomarkers considered an anti-inflammatory index (IL-4, IL-5, IL-10, IL-13, IL-1 RA) and a reduced risk of recurrence was indicated." (PMID 37510193, 2023). "The IL-6 and CXCL8 in blood samples and CCL2, IL-5 and IL-13 in hematoma samples did not have significant standardized loadings, and were therefore excluded from the statistical models." (PMID 24587250, 2014). "In the same study, a positive association between hematoma fluid CCL5 (also termed regulated on activation, normal T-cell expressed and secreted, RANTES) levels and recurrence as well as a negative association between IL-5, IL-13, IFN-γ and CXCL10 levels and recurrence was also indicated." (PMID 37510193, 2023).
hepatic granuloma (3 papers, 2015 to 2020). A granuloma located in the liver. "Recently, it has been shown that IL-33 and ST2 are involved in Th2-biased immune responses by triggering on the one hand IL-5 and IL-13 release and on the other hand hepatic granuloma pathology induced by Sj infection." (PMID 31200771, 2019). "IL-33 and its receptor ST2 are involved in Th2-biased immune responses through the release of IL-5 and IL-13 and subsequent hepatic granuloma pathology induced by Sj infection." (PMID 31200771, 2019). "We found that this sensor influences the formation of hepatic granuloma, altering local chemokine (CCL2, CCL3, and CXCL1) and cytokine (IL-5, IL-10, and IL-13) production, macrophage and neutrophil recruitment into the liver, and also is important for promoting collagen deposition." (PMID 32431709, 2020). "The present research shows that GR-MF derived from periovular granulomas of S. mansoni-infected mice produce IL-5 and eotaxin under TGF-β and IL-13 stimulation, and provides evidence that these molecules are relevant for eosinophil production and maintenance in hepatic granulomas." (PMID 26552582, 2015).
keratoconus (3 papers, 2016 to 2023). A degenerative, structural disorder of the eye, characterized by a cone-shaped protrusion of the cornea. "Partly in line with these results, increased tear levels of MMP-1, MMP-3, MMP-7, MMP-9, and MMP-13; IL-4, IL-5, IL-6, and IL-8, and TNF-α, -β were found in keratoconus." (PMID 26881061, 2016). "Elevated levels of interleukin- (IL-) 1b, IL-4, IL-5, IL-6, IL-8, and IL-17; tumor necrosis factor (TNF)-α, -β; interferon- (IFN-) γ; matrix metalloproteinase- (MMP-) 1, MMP-3, MMP-7, MMP-9, and MMP-13; Cathepsin B; and Lipocalin-1 have been found in the tears of patients with keratoconus." (PMID 26881061, 2016).
leukemia (3 papers, 2019 to 2023). A malignant (clonal) hematologic disorder, involving hematopoietic stem cells and characterized by the presence of primitive or atypical myeloid or lymphoid cells in the bone marrow and the blood. "Csf2rb encodes a common beta chain of the receptors of interleukin 3, interleukin 5, and granulocyte-macrophage colony-stimulating factor, and its partners’ expression has been described in specifically marking leukemia stem cells." (PMID 34638998, 2021). "There were also notable reductions in the leukemia-induced immunosuppressive cytokine milieu of Sig15 KO leukemia recipients, marked by decreases in IL6, LIF, and IL5 that all contribute to a more immune-privileged bone marrow niche." (PMID 37465593, 2023). "The human stromal cell line HS-5 expresses abundant FGF2, in addition to other soluble cytokines such as IL-5, IL-8 and HGF, and conditioned media (CM) from HS-5 is highly protective of leukemia cell lines." (PMID 30720426, 2019).
lymphedema (3 papers, 2022 to 2023). Excess fluid collection in tissues, causing swelling. "The number of CD4 cells that expressed Th2 cytokine IL4 and IL5 was increased in patients with lymphedema." (PMID 37886950, 2023). "Specifically, infiltration of Th2 CD4+ T cells characterized by signature cytokines such as IL-4, IL-5, and IL-13 promotes lymphedema but Treg cells inhibit the development of lymphedema." (PMID 37940849, 2023).
lymphoma (3 papers, 2018 to 2025). A malignant (clonal) proliferation of B- lymphocytes or T- lymphocytes which involves the lymph nodes, bone marrow and/or extranodal sites. "First, the systemic inflammatory cytokines produced by lymphoma cells, such as IL-4, IL-5, and TNF-α, can increase pruritus and facilitate the development of pruritic nodules." (PMID 39911286, 2025). "Pertinent to the findings presented here is that a clinical trial is underway exploring the efficacy of combining anti-PD-L1 agent (Avelumab) with recombinant IL-5 for subtypes of lymphoma (NCT03905135)." (PMID 37689790, 2023). "Thus, occurrence of lymphoma in an anti-IL-5-treated patient with HES is more likely to reflect progression of underlying disease (or its unmasking, following reduction of background treatment) than a treatment-effect on clonal T cells." (PMID 29682504, 2018).
malnutrition (3 papers, 2020 to 2023). Inadequate nutrition resulting from poor diet, malabsorption, or abnormal nutrient distribution. "Second, Type 2 cytokines involved are known to induce susceptibility to TB infection and disease However, our data suggest that even in the presence of TB disease, IL-4 and IL-5 levels are low, possibly due to the predominant influence of malnutrition in suppressing Th2 responses." (PMID 37324745, 2023). "Malnutrition by a low-protein diet in these animals increased the growth defects and the effects were seen already after 13 days, similar to what we see in our SG model, and it reduced the expression of the cytokines IL-4 and IL-5 compared to Giardia infected well-nourished mice." (PMID 34335577, 2021).
metastatic melanoma (3 papers, 2012 to 2021). A melanoma that has spread from its primary site to another anatomic site. "A recent clinical trial examined the IFN-γ/IL-5 ratio after polyclonal stimulation of PBMCs in patients with metastatic melanoma treated with immunomodulators given to restore the Th1/Th2 balance, and we performed a similar analysis of our data." (PMID 23186108, 2012). "The use of neutralizing antibodies directed against IL-5 may be useful to confirm the involvement of ILC2s in metastatic melanoma." (PMID 31849977, 2019).
nasal obstruction (3 papers, 2014 to 2025). "Elevated WBC may also imply increased levels of cytokines like IL-4, IL-5, and IL-13, resulting in more severe nasal obstruction, rhinorrhea, and loss of smell." (PMID 41473511, 2025).
nasopharyngitis (3 papers, 2022 to 2024). An inflammatory process that affects the nasopharynx. "Disadvantages of IL-5/IL-5R blockade are the high cost of treatment, regardless of the biologic used, and potential side effects such as headache, nasopharyngitis, and respiratory tract infections." (PMID 36035809, 2022). "Nasopharyngitis was cited in 20 studies from 19 published articles: Patients (13.55%, 729/5380) in the anti-IL-5 treatment group had a similar likelihood of suffering nasopharyngitis compared to those (15.45%, 734/475) in the placebo group (RR: 0.95, 95%CI: 0.86–1.04, P = 0.284, I2 = 11.4%)." (PMID 38308249, 2024).
nematode infection (3 papers, 2018 to 2024). "During nematode infection, there is an increase in IL-5 secretion, which acts on the recruitment and activation of eosinophils." (PMID 37888224, 2023). "Among these, IL-5 and IL-6 are the most critical cytokines in nematode infections." (PMID 38786064, 2024).
nephrotic syndrome (3 papers, 2008 to 2020). A collection of symptoms that include severe edema, proteinuria, and hypoalbuminemia; it is indicative of renal dysfunction. "It has been reported that children with nephrotic syndrome who had higher initial serum IgE levels, had higher relapsing rates, longer duration of steroid therapy before remission and higher serum IL-4 and IL-5 levels." (PMID 33330285, 2020). "Th2 cytokines (Interleukin (IL)-13, IL-4, IL-5) are increased in patients with nephrotic syndrome, and changes in vascular permeability have been reported, which are both involved in the complex pathogenesis of proteinuria in nephrotic syndrome." (PMID 31208104, 2019).
non-Hodgkin lymphoma (3 papers, 2023 to 2024). Distinct from Hodgkin lymphoma both morphologically and biologically, non-Hodgkin lymphoma (NHL) is characterized by the absence of Reed-Sternberg cells, can occur at any age, and usually presents as a localized or generalized lymphadenopathy associated with fever and weight loss. "Another difference from non-Hodgkin's lymphoma is that IL-5 (AUC = 0.73) and TNF-α (AUC = 0.74) in CML were also found to be useful in distinguishing bacterial infections in the lungs." (PMID 37114211, 2023).
ovarian carcinoma (3 papers, 2023 to 2024). A malignant neoplasm originating from the surface ovarian epithelium. "Furthermore, elevated level of serum cytokines IL-2, IL-5, IL-6, IL-10, and TNF-α in ovarian cancer patients, might be associated with ovarian cancer progression." (PMID 37322531, 2023). "Besides, elevated level of IL-5 and IL-15 in rEOC, it is very interesting to find the elevated level of IL-2 in their sera as IL-2 has promising therapeutic potential, a phase II clinical trial has shown its therapeutic benefits in platinum-resistant ovarian cancer patients." (PMID 37322531, 2023).
pemphigus (3 papers, 2016 to 2023). Pemphigus is a group of rare autoimmune diseases that cause blistering of the skin and mucous membranes (mouth, nose, throat, eyes, and genitals).This conditioncan occur at any age, but often strikes people in middle or older age. "Upregulation of the Th2 cytokines IL-4, IL-5, IL-10, and IL-13 has been described in pemphigus patients." (PMID 27304671, 2016). "Pemphigus is a TH2 cell-driven disease, a complex TH17/TFH17 cell–dominated disease, and these cells produce lineage-specific cytokines like IL-4, IL-5, IL-17, and IL-21, and desmoglein-specific antibodies." (PMID 37496035, 2023).
periodontal disease (3 papers, 2022 to 2024). "Conversely, the periodontal diseases are correlated to associated to a Th2 cell-mediated and an overexpression of the IL-4, IL-5, IL-6, and IL-10 mediators." (PMID 35735643, 2022).
preeclampsia (3 papers, 2019). Preeclampsia is a hypertensive disorder of pregnancy that is characterized by new-onset hypertension with proteinuria presenting after 20 weeks of gestation, and depending on mild or severe forms may initially present with severe headache, visual disturbances, and hyperreflexia. "Spontaneous secretion of IL-5 is lower in cell culture supernatants from PBMCs in preeclampsia than that in successful gestation, which manifests that systemic Th2 immunity of preeclamptic women is downregulated." (PMID 31100843, 2019). "The spontaneous in vitro secretion of IL-5 in the cell culture supernatants of blood mononuclear cells from normal pregnancy is higher than that from preeclampsia in humans." (PMID 33224295, 2019).
rhinosinusitis (3 papers, 2023 to 2025). "In fact, real life studies documented a significant improvement in quality of life, respectively assessed by SNOT-22 or Rhinosinusitis Outcomes Measure-31 (RSOM-31) after 6 and 12 months of treatment with the anti-IL5." (PMID 39404884, 2025).
sensitization (3 papers, 2013 to 2022). "Th2 cells produce IL-4, IL-5, IL-6, and IL-10, mediate humoral immunity, and are closely associated with the development of hypersensitivity reactions." (PMID 35419003, 2022).
septic shock (3 papers, 2013 to 2024). Shock caused by infection; frequently caused by gram negative bacteria, although some cases have been caused by other bacteria, viruses, fungi, and protozoa; characterized by fever, chills, tachycardia, tachypnea, and hypotension. "Less studied in septic shock are the TH2 cytokines IL4, IL5, IL9 and IL13." (PMID 24244449, 2013).
trauma (3 papers, 2015 to 2024). "It is known that IL-4 and IL-5 can increase the amount of nerve growth factor, which is secreted by astrocytes after neural trauma, independent of cell growth." (PMID 38334617, 2024). "Notably, complement activation is associated with various organ injuries, including acetaminophen-induced liver injury, and CSF2RB is a high-affinity receptor for IL-3, IL-5, and colony-stimulating factor." (PMID 26335687, 2015). "Levels of IFN-γ, IL-5, IL-7 were not different between trauma patients and healthy controls." (PMID 37120600, 2023).
type 1 diabetes (3 papers, 2010 to 2022). "Cumulatively, these findings suggest that IL-10 and IL-5 may play an important role in modulating the course of Type 1 diabetes in tolerized individuals." (PMID 20949090, 2010). "Both 1,25(OH)2D3 and TX527 also reduced the Th2 cytokines IL-13 and IL-4 and IL-5 (data not shown) in cultures from control and type 1 diabetes donor T cells, albeit not always statistically significant." (PMID 25279717, 2014). "In animal studies it has been shown that extracts of soluble S. mansoni worm or eggs antigens induced secretion of anti-inflammatory cytokines including IL-10, IL-4 and IL-5 from T cells and subsequently prevented development of type 1 diabetes in non-obese mice." (PMID 35077485, 2022).
Ulcer (3 papers, 2010 to 2025). "Perhaps locally applying IL-5 or IL-33 to an ulcer bed could attract eosinophils to promote fibrosis and closure (risky in terms of inflammation, but conceptually interesting)." (PMID 40860650, 2025).
abdominal aortic aneurysm (2 papers, 2019 to 2023). Enlargement and ballooning of the vessel that supplies arterial blood to the abdomen, pelvis and legs. "The group‐2 innate lymphoid cells (ILC2) slow abdominal aortic aneurysm (AAA) development by producing IL5 and IL13 to block smooth muscle cell (SMC) apoptosis and promote SMC proliferation." (PMID 36592421, 2023). "Clinical and experimental studies carried out in abdominal aortic aneurysms byhistological and immunohistochemical procedures proved that a predominantTh2-mediated immune response, mainly driven by IL-4, IL-5, or IL-10 cytokines,induces severe aneurysm formations." (PMID 30810667, 2019). "Development of abdominal aortic aneurysms (AAA) enhances lesion group‐2 innate lymphoid cell (ILC2) accumulation and blood IL5." (PMID 36592421, 2023).
acute GVHD (2 papers, 2024). "High levels of IL-5 were reported in patients with acute GVHD grades II-IV and fit with the low levels in home care patients." (PMID 39170616, 2024). "This means that our study did not have the opportunity to widen its considerations on more cytokines such as IFN-γ, G-CSF, GM-CSF, IL-2, IL-3, IL-5, and IL-13, which all have a known role in acute GVHD." (PMID 39728035, 2024). "We found higher levels of IFN-γ, IL-2, IL-5, IL-13, GM-CSF, and G-CSF, but lower VEGF in hospital-treated patients, which may contribute to acute GVHD grades II-IV." (PMID 39170616, 2024).
acute myeloid leukemia (2 papers, 2022 to 2023). Acute myeloid leukemia (AML) is a group of neoplasms arising from precursor cells committed to the myeloid cell-line differentiation. "In acute myeloid leukemia (AML), there is a significant enrichment of ILC1s in peripheral blood compared to healthy controls and a significant reduction in the production of IFN-γ, TNF, and IL-5/IL-13 in total ILCs defined as Lin-IL7R+." (PMID 38567059, 2023).
alopecia (2 papers, 2022). Hair loss usually from the scalp. "High serum levels of IL-4, IL-5, and IL-6 are also reported in patients with alopecia." (PMID 35273508, 2022).
amebiasis (2 papers, 2017 to 2023). A parasitic infectious disorder caused by amoebas. "In order to describe the immune response induced by IL-25 during amebiasis, we measured IL-4, IL-5, and IL-9 by enzyme-linked immunosorbent assay (ELISA) from cecal tissue lysates of mice after E. histolytica challenge with or without rIL-25 treatment." (PMID 28246365, 2017).
amyotrophic lateral sclerosis (2 papers, 2024 to 2025). Amyotrophic lateral sclerosis (ALS) is a neurodegenerative disease characterized by progressive muscular paralysis reflecting degeneration of motor neurons in the primary motor cortex, corticospinal tracts, brainstem and spinal cord. "A study indicated a beneficial role of IL-5 in amyotrophic lateral sclerosis (ALS), revealing that individuals with increased IL-5 levels tend to have extended survival." (PMID 40563358, 2025).
anaemia (2 papers, 2023). "Trend analysis of IL-2, IL-5, FGF, PDGF-bb, IL-17, CCL5, IL-4, IL-13, IFN-γ, IL-7 and TGF-β1 uncovered that as the severity of anemia increased, the concentrations of these inflammatory molecules decreased." (PMID 37143662, 2023).
angioedema (2 papers, 2013 to 2020). Swelling involving the deep dermis, subcutaneous, or submucosal tissues, representing localized edema. "Eosinophils release IL-5, C4, and platelet-activating factor, which may lead to increased vascular permeability and induce cutaneous lesions such as purpuric papules and angioedema." (PMID 24199910, 2013).
avian influenza (2 papers, 2015 to 2022). Infection of domestic and wild fowl and other birds with influenza A virus. "In contrast, H5N6 VLPs not only elicited higher neutralizing antibody titers, ranging from 640 to 1280, but also induced higher IL-2, IL-4, IL-5, IFN-γ and TNF production, thus indicating that H5N6 VLPs may be a potential vaccine candidate for broad-spectrum H5Nx avian influenza vaccines." (PMID 35632667, 2022).
bacterial sepsis (2 papers, 2023 to 2025). "This rarity is attributed to the distinct pathophysiology of parasite-induced systemic inflammation, which typically involves type-2 immune responses (IL-4/IL-5/IL-13 dominance) rather than the cytokine storms characteristic of bacterial sepsis." (PMID 41488892, 2025).